INS (insulin)
Diseases named in the same sentence as INS in open-access papers (continued):
Sharing a sentence is not in itself a finding about the gene and the disease.
type 2 diabetes (continued). "The childhood obesity epidemic is associated with progressive glucose intolerance and type 2 diabetes due to the increase in IR during puberty and the relative increase of insulin secretion that is insufficient for the high demand." (PMID 35586828, 2022). "Many people with type 2 diabetes require insulin therapy because of the gradual loss of islet beta cell function." (PMID 36203780, 2022). "Specifically, valsartan increased insulin secretion and sensitivity and reduced the risk of type 2 diabetes development in prediabetic individuals." (PMID 35733766, 2022). "The RPH subjects peaked in insulin concentration 60 min after stimulation, which is known to be more favorable than late peaks (e.g., 120th-minute peaks), which predict higher future type 2 diabetes risk in individuals with normal glucose tolerance." (PMID 36557270, 2022). "Our previous study based on the METSIM cohort showed that tyrosine, aspartate, and glutamate were significantly associated with decreases in insulin sensitivity and insulin secretion and consequently with increased risk of type 2 diabetes." (PMID 35050191, 2022). "The initial insulin reaction normalized, in people with type 2 diabetes, suggesting that a fatty pancreas is linked to type 2 diabetes." (PMID 36060389, 2022). "In conclusion, serum concentration of ADAM10 is increased in type 2 diabetes and is associated with glycemia and insulin therapy." (PMID 35705192, 2022). "Despite weight loss and restoration of insulin sensitivity, mice treated with minocycline remained glucose intolerant, which can contribute to elevated blood glucose and predispose to type II diabetes." (PMID 35784876, 2022). "A putative causal effect of fasting insulin adjusted for BMI and type 2 diabetes on PCOS was demonstrated." (PMID 35771237, 2022). "We therefore aimed to assess hypoglycemia risk with SUs and insulin therapy (in comparison with metformin) in people living with type 2 diabetes in a low-resource sub-Saharan African setting." (PMID 35450869, 2022). "The small integral membrane protein 29 (Smim29), showing a predicted missense mutation in the SHR-derived differential segment in BN.SHR20, has been recently associated to several obesity-related indices, type 2 diabetes, fasting insulin, and HDL cholesterol." (PMID 36014934, 2022). "Refined grains cause increased postprandial glucose and insulin concentrations, which are causally related to the development of obesity, type 2 diabetes, and cardiovascular diseases." (PMID 36411989, 2022). "Disturbed insulin signaling, associated with type 2 diabetes, affects the expression and metabolism of amyloid-β." (PMID 36232867, 2022). "This study investigated the relationship between a TYK2 promoter variant (TYK2PV) and insulin secretion in type 2 diabetes patients." (PMID 33799705, 2021). "Collectively, these studies show that exercise improves insulin sensitivity, regulates lipid and carbohydrate metabolism, and reduces the risk of type 2 diabetes." (PMID 33746668, 2021). "Type 2 diabetes (T2D) pathophysiology is linked to compromised insulin secretion caused by the progressive dysfunction and loss of pancreatic β‐cells." (PMID 33855202, 2021). "It is well established that diet-induced weight loss improves hepatic insulin sensitivity in individuals with type 2 diabetes." (PMID 34382579, 2021). "These functional regulatory variants were associated in GWAS with risk of type 2 diabetes and also affected insulin secretion and glycemic profile." (PMID 34440550, 2021). "One of the main causes of T2DM (type 2 diabetes mellitus) is insufficient insulin production to cover the needs of the organism." (PMID 33924206, 2021). "Here, we show that IRF3 expression in human adipose tissues is positively associated with insulin sensitivity and negatively associated with type 2 diabetes." (PMID 34091599, 2021).
type 2 diabetes (continued). "Compared with VAT, the enlargement of the SAT can be beneficial to patients by improving insulin sensitivity and reducing the risk of type II diabetes." (PMID 33679891, 2021). "The small GTPase ARF family member ARL15 gene locus is associated in population studies with increased risk of type 2 diabetes, lower adiponectin and higher fasting insulin levels." (PMID 34779483, 2021). "Diabesity is associated with the disruption of metabolic cell signaling pathways and attenuated insulin signaling, that is, insulin dysfunction, which raises the risk of type 2 diabetes." (PMID 33995826, 2021). "A SNP distant from the human insulin (INS) gene near the KRTAP5-6 gene confers increased susceptibility to type 2 diabetes when present on the paternal allele while decreased susceptibility when on the maternal allele." (PMID 34267199, 2021). "Daily administration of LU6 indicated beneficial effects in reducing postprandial hyperglycemia, endogenous insulin secretion, and islet regeneration, which can decrease the risk of developing type II diabetes in patients with impaired glucose tolerance." (PMID 33440620, 2021). "To date, type 2 diabetes mellitus (T2DM) has been considered a metabolic disease caused by defects in insulin secretion and action, which has been expanded to include a key role in inflammation." (PMID 34712322, 2021). "A sharp rise in insulin levels due to obesity and type 2 diabetes indicates an increase in the risk of cancer, especially newly developed diabetes, which seems to be closely related to pancreatic cancer." (PMID 34485124, 2021). "The study notes that DGKB variants have been associated with insulin clearance and, by interaction with insulin secretion, increased risk for type 2 diabetes." (PMID 33776816, 2021). "In the prospective multi-ethnic cohort study, the associations of metabolic perturbations in fatty acid metabolism with a 5-year risk of incident type 2 diabetes, before and after adjusting for insulin sensitivity and IR, were investigated." (PMID 34209638, 2021). "Impaired insulin secretion from pancreatic beta cells is characteristic for type 2 diabetes (T2D), and is the main cause of glucose intolerance." (PMID 34638768, 2021). "Insulin-treated patients with type 2 diabetes (T2D) are at risk of hypoglycemia, which is associated with an increased risk of cardiovascular disease and mortality." (PMID 34952579, 2021). "Coffee and beta cells: Loss of functional beta cell mass in relation to insulin requirements is the critical process causing type 2 diabetes." (PMID 33807132, 2021). "This indicates that our selection criteria, of diagnosis between the ages of 31 and 50 years and insulin treatment, includes a mixture of both type 1 diabetes and type 2 diabetes cases (all associations p < 0.001)." (PMID 34272580, 2021). "Type 2 diabetes mellitus (T2DM) is a degenerative disease caused by impairment in insulin action and pancreatic β-cell function, characterized by the inability to maintain glucose homeostasis." (PMID 34195182, 2021). "First, since this was a cross-sectional study, thecausal association between insulin therapy and carotid atherosclerotic lesions in type 2 diabetes cannot be verified and needs further clarification in future prospective studies." (PMID 33598483, 2021). "Because the variants within the SNP-SELEX data are cis-regulatory variants near type-2 diabetes risk loci, many of the transcription factors were associated with related processes, such as insulin and glucose metabolism or adipogenesis." (PMID 34570765, 2021). "By reducing hyperglycemia, these drugs likely facilitate weight loss; both are proposed mechanisms for improved insulin sensitivity in adults with type 2 diabetes." (PMID 33828529, 2021). "Type 2 diabetes (T2D) has been determined to be caused by the body’s inability to use insulin effectively, and it affects the vast majority of individuals with diabetes." (PMID 34501750, 2021).
type 2 diabetes (continued). "Overexpression of the α2-adrenergic receptor on the β-cells is known to impair insulin granule docking at the plasma membrane, reduce β-cell exocytosis and insulin secretion, and increase type 2 diabetes risk." (PMID 34354571, 2021). "CVD is commonly caused by atherosclerosis whereas type 2 diabetes (T2D) is characterized by elevated blood glucose raised mainly from defects in insulin secretion and insulin resistance." (PMID 33794782, 2021). "Type 2 diabetes is a complex metabolic disorder associated with developing insulin resistance, impaired increased oxidative stress, inflammation, insulin signaling, abnormal glucose metabolism, and so on." (PMID 34707780, 2021). "Elevated basal insulin secretion under fasting conditions along with deficient stimulated insulin secretion is an important indication of type 2 diabetes." (PMID 34072220, 2021). "Reduced insulin sensitivity in critical organs such as adipose tissues, muscle, and liver is a hallmark of type 2 diabetes." (PMID 34206641, 2021). "Low plasma aldosterone levels have been described in patients with type 1 diabetes and elevated aldosterone is associated with type 2 diabetes by affecting insulin sensitivity." (PMID 34828323, 2021). "Individuals with type 2 diabetes have an increased risk for the development of cardiovascular disease compared to individuals with normal insulin sensitivity." (PMID 34350730, 2021). "Failure to appropriately secrete insulin results in impaired blood glucose control and is a hallmark of type-2 diabetes (T2D)." (PMID 33146746, 2021). "It is highly associated with insulin resistant states, including the metabolic syndrome, type 2 diabetes mellitus (T2DM), and obesity." (PMID 34209858, 2021). "In Type 2 diabetes-related studies, the levels of butyrate and propionate in feces were related to the patient’s insulin response and risk of disease." (PMID 34233671, 2021). "With respect to metabolic health outcomes in Latino youth, higher morning serum cortisol at baseline and a 2-year increase in cortisol was associated with type 2 diabetes risk factors, including higher fasting glucose and lower insulin sensitivity." (PMID 33832509, 2021). "In the present study, we investigated the prevalence of clinically significant arrhythmias in insulin-treated patients with type 2 diabetes and the association between arrhythmic events and episodes of hypoglycemia and glycemic variability." (PMID 34952579, 2021). "The present analysis demonstrates that risk is even further magnified in insulin-treated patients with type 2 diabetes and ACS, with a 3-year incidence of cardiovascular death, myocardial infarction, or stroke of approximately 20%." (PMID 34158057, 2021). "Type 2 diabetes is a risk factor for Alzheimer’s disease (AD), and AD brain shows impaired insulin signalling." (PMID 33597002, 2021). "This poor insulin signalling is a foundational aspect of the pathogenesis of metabolic syndrome, obesity, type 2 diabetes, and most chronic diseases and comorbidities linked with an unhealthy diet, e.g., cardiovascular diseases and cancer." (PMID 34579001, 2021). "Previous studies showed that D2 has higher insulin and glucose levels and is predisposed to develop diet-induced type 2 diabetes." (PMID 34637789, 2021). "It is well known that metabolic disorders with elevated insulin levels, such as obesity, metabolic syndrome, and type-2-diabetes, are associated with and accompanied by chronic subclinical inflammation." (PMID 33922802, 2021). "Type 2 diabetes is caused by hyperinsulinemia and insulin levels are directly affected by carbohydrate consumption." (PMID 34068325, 2021). "Type 2 diabetes (T2D) is caused by loss of insulin sensitivity in adipocytes, muscle, and other insulin-dependent cells, leading to loss of effective control of glucose concentration, resulting in inflammation and disruption of metabolic pathways." (PMID 34829877, 2021).
type 2 diabetes (continued). "Poor sleepers tend to have a higher risk of obesity and type 2 diabetes as suppression of slow-wave sleep leads to decreased insulin sensitivity and leptin levels and increased ghrelin." (PMID 34612827, 2021). "Compared with the subjects without insulin exposure, there was an approximate 180% increased risk of all-cause mortality in those with high levels of insulin exposure in type 2 diabetes." (PMID 33598483, 2021). "A number of clinical studies have reported associations between CER[NS] species and type-2 diabetes risk, incidence, and/or disease markers; such as fasting glucose and insulin, HOMA-IR and HOMA-B, and insulin sensitivity." (PMID 33437986, 2021). "Myoinositol, an isomer of inositol, is one of the intracellular mediators of the insulin signal and is associated with insulin sensitivity in type 2 diabetes." (PMID 34836042, 2021). "The onset of Type II Diabetes mellitus is marked by defective secretion of insulin and apoptotic loss of the islet cells." (PMID 34124059, 2021). "From the study findings, the multivariate model with Genotype, TG and Insulin model showed an association between genotype and type-2 diabetes risk." (PMID 34162950, 2021). "The use of insulin was also reported to decrease cancer risk in a human study in Chinese patients with type 2 diabetes." (PMID 34212132, 2021). "Interviews with patients with Type 2 diabetes revealed 47/59 (80%) were afraid of pain associated with needles and injections; this was 100% in a sub-sample (n = 32) who refused insulin therapy despite medical advice." (PMID 34111207, 2021). "Lifestyle interventions with weight loss can improve insulin sensitivity in type 2 diabetes (T2D), but mechanisms are unclear." (PMID 34940592, 2021). "Emergency BS, revisional BS, insulin-treated type 2 diabetes, and untreated obstructive sleep apnoea were associated with increased complications on multivariable analysis." (PMID 34328624, 2021). "Type 2 diabetes is characterized by insulin deficiency and resistance to the physiological effects of insulin, resulting in hyperglycemia." (PMID 34174848, 2021). "Initially, variants at type 2 diabetes risk loci affecting insulin secretion were tested for their association with birthweight and it was found that fetal risk alleles at the CDKAL1 and HHEX-IDE loci were associated with a lower birthweight." (PMID 33569631, 2021). "Collectively, these studies show that mitochondrial dysfunction leads to impaired insulin signaling pathways and increases the risk of type 2 diabetes." (PMID 33746668, 2021). "(c) Therapeutic use of insulin in type 2 diabetes as a marker for insulin deficiency and thus as an independent risk factor for DR." (PMID 34912295, 2021). "The study results showed that r-metHuLeptin does not have weight-loss–independent, clinically important effects on insulin sensitivity in obese subjects with newly diagnosed type 2 diabetes." (PMID 34084149, 2021). "Seung-Hong Lee and co-workers showed that the treatment of type 2 diabetic mice with a Dieckol-rich extract from Ecklonia cava caused a significant reduction of blood glycosylated hemoglobin and plasma insulin levels and an improvement of glucose tolerance." (PMID 34443409, 2021). "The ‘pre-diabetic’ condition is characterised by insulin resistance, which eventually triggers beta cell failure, loss of compensatory insulin secretion and the onset of frank type 2 diabetes." (PMID 33805674, 2021). "In Asian Indians, a cross-sectional study of about 20,000 patients with type 2 diabetes showed a similar relationship with DR and the insulin deficient cluster." (PMID 34912295, 2021). "The gene encodes the zinc transporter-8 (ZnT8), delivering Zn2+ ions from the cytoplasm to the insulin secretory granules in pancreatic β cells, affecting the risk of type 2 diabetes." (PMID 34959365, 2021).
type 2 diabetes (continued). "Obesity and type 2 diabetes are associated with disturbances in insulin-regulated glucose and lipid fluxes and severe comorbidities including cardiovascular disease and steatohepatitis." (PMID 34836963, 2021). "It has been shown that insulin use is associated with high fracture risk in patients with type 2 diabetes." (PMID 34200167, 2021). "Taken as a whole, it is clear that both lower birthweight and type 2 diabetes reflect, in part, a shared genetic predisposition to reduced insulin secretion." (PMID 33569631, 2021). "In contrast, diets with high GI have been associated with type 2 diabetes and cardiovascular diseases due to their effect on blood glucose and insulin levels." (PMID 34684378, 2021). "In insulin-treated patients with type 2 diabetes, spontaneous episodes of hypoglycemia are associated with an increased incidence of ventricular premature beats and nocturnal bradycardia." (PMID 34085953, 2021). "Further, there were also records associated with glucose metabolism (type 2 diabetes, positive regulation of glucose metabolic process, signaling of insulin via INSR, IGF1R, PKB, Pi3K, and MAPK)." (PMID 33445738, 2021). "Chronic elevation of IL-6 is associated with decreased insulin sensitivity and the development of type 2 diabetes and cardiovascular disease." (PMID 34684621, 2021). "The second was on chromosome 11p15.5, near INS, where the primary type 2 diabetes association co-localised with the secondary type 1 diabetes association (H4PP=0.95)." (PMID 33830302, 2021). "This is a novel case of a patient with Type II diabetes mellitus prescribed metformin and insulin who developed MALA-induced, reversible vision loss with the highest measured, concurrent metformin concentration." (PMID 34437006, 2021). "Type 2 Diabetes (T2D) is a chronic, complex disorder which is caused by defective insulin secretion by pancreatic β-cells as well as weak insulin action to its responsive tissues." (PMID 34017037, 2021). "Hormonal disorders cause an increase in body mass, influence distribution of adipose tissue, reduce energy expenditure and decrease insulin secretion and sensitivity of cells to this hormone, all of which predispose to the development of type 2 diabetes." (PMID 34769939, 2021). "In humans, mutations in several clock genes are strongly associated with obesity, INS resistance, and type 2 diabetes." (PMID 33815298, 2021). "Here, we report a case, in which a type 2 diabetes patient suffered an acute aggravation of pre-existing high-risk PDR after the insulin IT." (PMID 33607771, 2021). "Medications broadly increasing 5‐HT bioavailability are effective for treating human obesity and commonly improve insulin sensitivity and glycaemic control in obese patients with type 2 diabetes by promoting weight loss." (PMID 33909316, 2021). "Alterations in lipid metabolism within beta cells and islets contributes to dysfunction and apoptosis of beta cells, leading to loss of insulin secretion and the onset of type 2 diabetes." (PMID 34203703, 2021). "In type 1 diabetes which is as a result of absolute insulin deficiency, treatment is based on exogenous insulin therapy, while in type 2 diabetes, treatment is usually based on antidiabetic drugs and lifestyle modifications." (PMID 34535145, 2021). "Lyplal1 has been associated with type 2 diabetes including through use of first-phase insulin secretion as a marker to identify candidate interacting SNPs." (PMID 33784857, 2021). "In many cases, the observed phenotypic changes were more pronounced when mice were maintained on a high-fat (obesogenic) diet which causes impaired glucose tolerance and insulin sensitivity, two hallmarks of type 2 diabetes (T2D)." (PMID 34354673, 2021). "In contrast to previous studies, the present study included only insulin-treated patients with type 2 diabetes with a low HbA1c and, accordingly, a high risk of hypoglycemia." (PMID 34085953, 2021).